MAP2K1 (mitogen-activated protein kinase kinase 1)
Description:
Dual specificity protein kinase which acts as an essential component of the MAP kinase signal transduction pathway. Binding of extracellular ligands such as growth factors, cytokines and hormones to their cell-surface receptors activates RAS and this initiates RAF1 activation. RAF1 then further activates the dual-specificity protein kinases MAP2K1/MEK1 and MAP2K2/MEK2. Both MAP2K1/MEK1 and MAP2K2/MEK2 function specifically in the MAPK/ERK cascade, and catalyze the concomitant phosphorylation of a threonine and a tyrosine residue in a Thr-Glu-Tyr sequence located in the extracellular signal-regulated kinases MAPK3/ERK1 and MAPK1/ERK2, leading to their activation and further transduction of the signal within the MAPK/ERK cascade. Activates BRAF in a KSR1 or KSR2-dependent manner; by binding to KSR1 or KSR2 releases the inhibitory intramolecular interaction between KSR1 or KSR2 protein kinase and N-terminal domains which promotes KSR1 or KSR2-BRAF dimerization and BRAF activation. Depending on the cellular context, this pathway mediates diverse biological functions such as cell growth, adhesion, survival and differentiation, predominantly through the regulation of transcription, metabolism and cytoskeletal rearrangements. One target of the MAPK/ERK cascade is peroxisome proliferator-activated receptor gamma (PPARG), a nuclear receptor that promotes differentiation and apoptosis. MAP2K1/MEK1 has been shown to export PPARG from the nucleus. The MAPK/ERK cascade is also involved in the regulation of endosomal dynamics, including lysosome processing and endosome cycling through the perinuclear recycling compartment (PNRC), as well as in the fragmentation of the Golgi apparatus during mitosis.
Synonyms: MKK1; MEK1; PRKMK1; MAPKK1; CFC3; MEL
Tractability: Small molecule: an approved drug acts on it; a structure with a bound ligand is known; a high-quality ligand is known; it has a high-quality binding pocket; it belongs to a druggable protein family. Antibody: UniProt places it where antibodies can reach, with high confidence; its Gene Ontology location is reachable by antibodies, with high confidence; the Human Protein Atlas places it where antibodies can reach. PROTAC: it is named in the literature on targeted protein degradation; ubiquitination databases record sites on it; its protein half-life has been measured; a small molecule that binds it is known.
Target class: STE protein kinase group; Kinase; Enzyme; Protein Kinase; STE protein kinase STE7 family
Chemical probes: MEK inhibitor I, PD080692, PD080971, PD081047, PD081201, PD081297, PD081695, PD082452, PD082488, PD082554, PD082795, PD082801, PD083101, PD083281, PD083658, PD083765, PD083897, PD083984, PD085011, PD085378, and 2 more
Gene: Protein-coding gene on chromosome 15 (66,386,825 to 66,491,656, forward strand). Ensembl gene ENSG00000169032.
Subcellular location: Cytoplasm, cytoskeleton, microtubule organizing center, centrosome; Cytoplasm, cytoskeleton, microtubule organizing center, spindle pole body; Cytoplasm; Nucleus; Membrane
Subcellular location (Human Protein Atlas): Cytosol; Plasma membrane; Basal body
Pathways (Reactome):
Disease: Paradoxical activation of RAF signaling by kinase inactive BRAF; Signaling by BRAF and RAF1 fusions; Signaling by MAP2K mutants; Signaling by RAF1 mutants; Signaling by high-kinase activity BRAF mutants; Signaling by moderate kinase activity BRAF mutants; Signaling downstream of RAS mutants; Uptake and function of anthrax toxins
Signal Transduction: Frs2-mediated activation; MAP2K and MAPK activation; MAPK3 (ERK1) activation; Negative feedback regulation of MAPK pathway; RAF activation
Developmental Biology: Signal transduction by L1
Immune System: MAP3K8 (TPL2)-dependent MAPK1/3 activation
Gene Ontology:
Molecular function: MAP kinase kinase activity; MAP-kinase scaffold activity; protein binding; protein kinase activator activity; protein serine/threonine kinase activator activity; scaffold protein binding; protein kinase activity; protein serine/threonine kinase activity; protein serine/threonine/tyrosine kinase activity; ATP binding; mitogen-activated protein kinase kinase kinase binding; protein kinase binding; protein serine kinase activity; protein tyrosine kinase activity; protein-containing complex binding; small GTPase binding
Biological process: cellular senescence; negative regulation of cell population proliferation; positive regulation of DNA-templated transcription; positive regulation of ERK1 and ERK2 cascade; positive regulation of gene expression; positive regulation of protein serine/threonine kinase activity; chemotaxis; ERK1 and ERK2 cascade; MAPK cascade; neuron differentiation; regulation of early endosome to late endosome transport; regulation of Golgi inheritance; regulation of stress-activated MAPK cascade; signal transduction; ERBB signaling pathway; ERBB2-ERBB3 signaling pathway; Golgi inheritance; insulin-like growth factor receptor signaling pathway; melanosome transport; myelination; negative regulation of gene expression; negative regulation of homotypic cell-cell adhesion; negative regulation of hypoxia-induced intrinsic apoptotic signaling pathway; neuromuscular junction development; neuron projection morphogenesis; and 15 more
Cellular component: ciliary basal body; cytoplasm; cytosol; endoplasmic reticulum; membrane; nucleus; plasma membrane; early endosome; focal adhesion; Golgi apparatus; late endosome; mitochondrion; axon; cell cortex; centrosome; dendrite; dendrite cytoplasm; glutamatergic synapse; microtubule; perikaryon; perinuclear region of cytoplasm; postsynaptic density
Genetic constraint (gnomAD): Loss-of-function variants: 13 observed, 40.14 expected, observed/expected ratio (o/e) 0.32, 90% interval 0.21 to 0.51. The upper end of that interval is the gene's LOEUF score, 0.51, which puts it in group 2 of 6, group 1 being the genes least tolerant of losing a copy. Missense variants: 242 observed, 463.47 expected, observed/expected ratio (o/e) 0.52, 90% interval 0.47 to 0.58. Synonymous variants: 172 observed, 178.55 expected, observed/expected ratio (o/e) 0.96, 90% interval 0.85 to 1.09.
Gene-disease validity (ClinGen):
ClinGen rates the evidence that MAP2K1 causes each of these diseases.
cardiofaciocutaneous syndrome (autosomal dominant): Definitive. Cardiofaciocutaneous (CFC) syndrome is a RASopathy characterized by craniofacial dysmorphology, congenital heart disease, dermatological abnormalities (most commonly hyperkeratotic skin and sparse, curly hair), growth retardation and intellectual disability.
Noonan syndrome (autosomal dominant): Limited. Noonan Syndrome (NS) is characterized by short stature, typical facial dysmorphism and congenital heart defects.
Noonan syndrome with multiple lentigines (autosomal dominant): Limited. A rare multisystem genetic disorder characterized by lentigines, hypertrophic cardiomyopathy, short stature, pectus deformity, and dysmorphic facial features.
Costello syndrome (autosomal dominant): Disputed. Costello syndrome (CS) is a rare multisystemic disorder characterized by failure to thrive, short stature, developmental delay or intellectual disability, joint laxity, soft skin, and distinctive facial features.
Cancer hallmarks: genome instability and mutations; angiogenesis (promotes); tumour promoting inflammation (promotes); escaping programmed cell death (promotes); invasion and metastasis (promotes); change of cellular energetics; proliferative signalling (promotes); genome instability and mutations (suppresses)
Homologues: Orthologues: chimpanzee MAP2K1 (100% identical), pig MAP2K1 (100% identical), macaque MAP2K1 (99% identical), dog MAP2K1 (99% identical), rat Map2k1 (99% identical), mouse Map2k1 (99% identical), guinea pig MAP2K1 (98% identical), rabbit MAP2K1 (93% identical), tropical clawed frog map2k1 (92% identical), zebrafish map2k1 (88% identical), Drosophila melanogaster Dsor1 (62% identical), Caenorhabditis elegans mek-2 (53% identical). Paralogues in human: MAP2K2 (82% identical), MAP2K5 (39% identical), MAP2K7 (35% identical), MAP2K4 (34% identical), MAP3K4 (24% identical), MAP3K2 (24% identical), MAP3K3 (24% identical), NEK1 (15% identical).
Diseases named in the same sentence as MAP2K1 in open-access papers:
MAP2K1 is named in the same sentence as 380 diseases in open-access papers, as found by Europe PMC text mining. Sharing a sentence is not in itself a finding about the gene and the disease. The quoted sentences say what the papers report.
melanoma (328 papers, 2008 to 2026). A malignant, usually aggressive tumor composed of atypical, neoplastic melanocytes. "Class II and III driven MAP2K1-mutated melanomas have significant metastatic potential, particularly when accompanied by TERT-p mutations." (PMID 40107205, 2025). "MAP2K1 (MEK1), which is infrequently mutated in melanoma, colon and lung cancer, is involved in the RAS/MAPK signaling pathway, influencing various cellular processes such as growth, proliferation, and survival." (PMID 39844043, 2025). "In our study, Class II and III MAP2K1-driven tumours exhibited spitzoid histomorphology in all nevi and three-quarters of melanocytomas and melanomas, compared to half of the tumours with Class I MAP2K1 mutations and concomitant MAPK mutations." (PMID 40107205, 2025). "The median ages of patients with Class II and III MAP2K1 mutations, in both the non-melanoma and melanoma groups, were notably higher than in the typically younger individuals with Spitz tumours." (PMID 40107205, 2025). "Aggressive behaviour of Class II or III MAP2K1-driven tumours is likely stimulated by additional oncogenic alterations, as all these melanomas also harboured TERT-p mutations." (PMID 40107205, 2025). "In melanomas, Class I MAP2K1 mutations have been identified as secondary oncogenic drivers, typically occurring alongside BRAF, NRAS, or NF1 mutations." (PMID 40107205, 2025). "MEK inhibitors are successful in treating Langerhans cell histiocytosis with MAP2K1 mutations (evidence level 3A), but their efficacy in melanoma remains uncertain." (PMID 39564955, 2024). "Clonal MAPK-pathway activating mutations in the MAP2K1 (MEK1) gene are present in approximately 9% of cutaneous melanomas." (PMID 39314226, 2024). "Our case showed MAP2K1 gene mutations and p16INK4a loss, which are commonly found in melanoma malignancies." (PMID 39329865, 2024). "This illustrates the utility of NGS profiles that include class-1/2 MAP2K1-mutations in patients with melanoma and other malignancies to provide valuable information on a potentially active individualized treatment option." (PMID 39314226, 2024). "MAP2K1 mutations are enriched in BRAF-mutant melanoma and function as an innate or adaptive resistance mechanism to BRAF inhibition." (PMID 36901951, 2023). "MAP2K1/2 genes are mutated in approximately 8% of melanoma patients; however, the impact of MAP2K1/2 gene alterations on the efficiency of immunotherapy has not been clarified." (PMID 35069558, 2021). "In cases where BRAF is inhibited, CRAF can activate downstream MAP2K1 with RAS mutation in melanoma." (PMID 34831420, 2021). "MAP2K1/2 mutations were identified as an independent predictive factor for anti-CTLA-4 therapy in melanoma patients." (PMID 35069558, 2021). "Our aim is to clarify the impact of MAP2K1/2 gene alterations on the efficiency of immunotherapies and to provide guidance for treatment decision-making in MAP2K1/2-mutated melanomas." (PMID 35069558, 2021). "Our results indicated that patients with MAP2K1/2-mutated melanoma who received anti-CTLA-4 therapy had better OS." (PMID 35069558, 2021). "The occurrence of MAP2K1/2 mutations was identified as a mechanism related to BRAF inhibitor resistance in melanoma." (PMID 35069558, 2021). "MAP2K1/2-mutated cases constitute approximately 8% of all melanoma patients, and the clinical studies of this population has been rarely reported." (PMID 35069558, 2021). "Further studies are also needed to elucidate the mechanisms underlying the clinical benefits of anti-CTLA-4 therapy in MAP2K1/2-mutated melanoma." (PMID 35069558, 2021). "We found that MAP2K1/2-mutated melanomas exhibited higher TMB levels than MAP2K1/2-wild-type melanomas." (PMID 35069558, 2021). "To evaluate the impact of MAP2K1/2 mutations on the transcription of immunity-related genes in melanoma, we integrated and analysed the gene expression data for patients from four clinical cohorts and the TCGA-SKCM cohort." (PMID 35069558, 2021).
melanoma (continued). "This study can also provide a guideline for making treatment decisions for patients with MAP2K1/2-mutated melanoma." (PMID 35069558, 2021). "TMB analysis also revealed that melanoma patients harbouring MAP2K1/2 mutations have a higher level of TMB." (PMID 35069558, 2021). "In other words, anti-CTLA-4 therapy was superior to anti-PD-1/L1 therapy for patients with MAP2K1/2-mutated melanoma." (PMID 35069558, 2021). "In this study, the clinical benefits (OS) of anti-CTLA-4 and anti-PD-1 therapies in patients with MAP2K1/2-mutated melanoma were compared in a pooled cohort comprising a combination of six cohorts." (PMID 35069558, 2021). "Since no effective targeted therapeutic drugs have been reported against MAP2K1/2-mutated melanomas, ICIs are still considered as the preferred systemic treatment for these patients." (PMID 35069558, 2021). "First, we introduced the MAP2K1 p.E203K mutation (c.G607A) into human A375 melanoma cells carrying a homozygous BRAF V600E mutation (c.T1799A)." (PMID 32242071, 2020). "Follow-up data, which was not available in this study, will be important to obtain for this cohort of MAP2K1-mutated melanoma to correlate with prognosis and therapeutic outcomes." (PMID 32483240, 2020). "Herein, we report a series of melanomas with MAP2K1 in-frame deletions distinct from other driver mutations of melanoma." (PMID 32483240, 2020). "Other series revealed MAP2K1 point mutations in two of 253 melanomas and MAP2K1 mutations of unspecified type in 21 of 356 melanomas." (PMID 32483240, 2020). "In general, MAP2K1/2 mutations in BRAF V600E melanomas are linked to both intrinsic and acquired resistance to BRAF inhibitors." (PMID 32850962, 2020). "In particular, melanoma patients have a higher frequency of MAP2K1 mutations/CNVs compared to MAP2K2 mutations/CNVs." (PMID 32850962, 2020). "Melanomas also contain MAP2K1 (MEK1) mutations, with prior reports consisting almost entirely of missense mutations characterized as secondary oncogenic driver mutations." (PMID 32483240, 2020). "Melanomas with MAP2K1 in-frame deletions show distinct mutational profiles and correlate closely with prior functional studies of MAP2K1 deletion." (PMID 32483240, 2020). "Previously reported genomic alterations in MAP2K1 in melanoma have consisted almost entirely of point mutations, with only a single report of in-frame deletion, and generally have been characterized as secondary driver mutations." (PMID 32483240, 2020). "Most reported MAP2K1 mutations have accompanied other driver mutations of melanoma including BRAF, NRAS, and NF1." (PMID 32483240, 2020). "The authors of this study reviewed the TCGA database and identified MAP2K1 alterations in 7% of melanomas, consisting mostly of point mutations with some amplifications and no in-frame deletions, with nearly all co-occurring with BRAF or NRAS mutations." (PMID 32483240, 2020). "In another study of 127 melanomas, eight had MAP2K1 point mutations and two had MAP2K2 point mutations; these alterations were associated with constitutive ERK phosphorylation, and most co-occurred with either BRAF or NRAS mutation." (PMID 32483240, 2020). "A case report of cutaneous melanoma metastases sampled over time revealed a MAP2K1 (F53Y) missense mutation paired with a BRAF fusion." (PMID 32483240, 2020). "This close correlation with prior functional studies and the independence from other MAPK driver mutations support the concept that MAP2K1 in-frame deletions characterize a distinct subtype of triple wild-type melanoma." (PMID 32483240, 2020). "Although MAP2K1 mutations have been observed at a lower frequency, they have been identified in several cancers including lung adenocarcinoma, melanoma and gastric cancer." (PMID 31827134, 2019).